MYH7B (myosin heavy chain 7B)
Description:
Involved in muscle contraction.
Synonyms: KIAA1512; dJ756N5.1; MYH14; MHC14; lncMYH7b
Tractability: Small molecule: an approved drug acts on it. Antibody: UniProt places it where antibodies can reach, with high confidence. PROTAC: ubiquitination databases record sites on it.
Gene: Protein-coding gene on chromosome 20 (34,955,810 to 35,002,437, forward strand). Ensembl gene ENSG00000078814.
Subcellular location: Membrane
Gene Ontology:
Molecular function: protein binding; actin filament binding; microfilament motor activity; ATP binding; cytoskeletal motor activity
Biological process: regulation of calcium-mediated signaling; regulation of CAMKK-AMPK signaling cascade; regulation of cardiac muscle cell contraction; regulation of cytosolic calcium ion concentration
Cellular component: cytoplasm; myosin filament; myosin II complex; cardiac myofibril; membrane; myofibril; myosin complex
Genetic constraint (gnomAD): Loss-of-function variants: 205 observed, 226.77 expected, observed/expected ratio (o/e) 0.9, 90% interval 0.81 to 1.01. The upper end of that interval is the gene's LOEUF score, 1.01, which puts it in group 4 of 6, group 1 being the genes least tolerant of losing a copy. Missense variants: 2,652 observed, 2,645.7 expected, observed/expected ratio (o/e) 1, 90% interval 0.97 to 1.03. Synonymous variants: 1,193 observed, 1,100.5 expected, observed/expected ratio (o/e) 1.08, 90% interval 1.03 to 1.14.
Homologues: Orthologues: macaque MYH7B (99% identical), chimpanzee MYH7B (98% identical), pig MYH7B (97% identical), dog MYH7B (97% identical), guinea pig MYH7B (96% identical), mouse Myh7b (96% identical), rabbit MYH7B (95% identical), rat Myh7b (94% identical). Paralogues in human: MYH7 (69% identical), MYH6 (68% identical), MYH2 (68% identical), MYH1 (67% identical), MYH8 (67% identical), MYH3 (67% identical), MYH4 (67% identical), MYH13 (66% identical), MYH15 (60% identical), MYH11 (41% identical), MYH9 (41% identical), MYH10 (41% identical), and 32 more.
Diseases named in the same sentence as MYH7B in open-access papers:
MYH7B is named in the same sentence as 36 diseases in open-access papers, as found by Europe PMC text mining. Sharing a sentence is not in itself a finding about the gene and the disease. The quoted sentences say what the papers report.
hearing loss (3 papers, 2014 to 2024). "In this study, we sought to further elucidate the biological role of MYH7b by examining the molecular and cellular impacts of the two MYH7b hearing loss–associated mutations, D515N and R1651Q." (PMID 36963494, 2023). "The work presented in this study lays the foundation for this understanding, and the observation that these hearing loss–associated mutations have distinct molecular and cellular phenotypes argues that MYH7b has a role in auditory tissues." (PMID 36963494, 2023). "Using exome sequencing we have identified defects in a myosin II gene, MYH7B, as the likely contributors to hearing loss in one family." (PMID 25528277, 2014). "Our results extend the role of cytoskeletal proteins in hearing and offer the possibility that mutations in the MYH7B gene may constitute a rare cause of hearing loss." (PMID 25528277, 2014). "However, MYH7b, an evolutionarily ancient member of this myosin family, has been detected in mammalian nonmuscle tissues, and mutations in MYH7b are linked to hereditary hearing loss in compound heterozygous patients." (PMID 36963494, 2023). "Notably, glutamine repeats contribute to protein aggregates that characterize many neurodegenerative diseases, presenting a reasonable hypothesis for the molecular pathogenicity of the MYH7b R1651Q mutation in hearing loss." (PMID 36963494, 2023). "Among them, MYH7B has also been detected in non-muscle tissues of mammals, and MYH7B mutations are associated with hereditary hearing loss in compound heterozygous patients." (PMID 38338049, 2024). "The MYH7B gene has not been previously implicated in hearing loss but has been linked to differentiation of inner ear hair cells and shown to control actin networks within neurons." (PMID 25528277, 2014). "Although several other myosin heavy chain genes have been previously implicated in hearing loss, the MYH7B gene has not." (PMID 25528277, 2014).
dilated cardiomyopathy (2 papers, 2017 to 2023). Cardiomyopathy which is characterized by dilation and contractile dysfunction of the left and right ventricles. "Moreover, forced cardiac expression of MYH7b protein in a transgenic mouse model resulted in a severe dilated cardiomyopathy, underscoring the importance of evolutionary silencing of MYH7b protein production in the mammalian heart." (PMID 36334627, 2023).
hypertrophic cardiomyopathy (2 papers, 2017 to 2025). A condition in which the myocardium is hypertrophied without an obvious cause. "Variants in MYH7B, which hosts MIR499a, have been associated with both hypertrophic cardiomyopathy and oxidative stress–related metabolic pathways." (PMID 41226486, 2025). "MYH7B encodes a myosin heavy chain isoform implicated not only in hypertrophic cardiomyopathy but also in metabolic regulation." (PMID 41226486, 2025).
melanoma (2 papers, 2018 to 2019). A malignant, usually aggressive tumor composed of atypical, neoplastic melanocytes. "However, the variants associated with MYH7b are hypothesized to be positional markers for genes associated with melanoma-like ASIP, a pigmentation gene in the same chromosomal region as MYH7b, rather than a disease modifying variant." (PMID 30836986, 2019). "This gene is not well studied in CRC but has been studied in melanoma, and MYH7B SNPs have been associated with increased melanoma risk." (PMID 29547645, 2018).
Stroke (2 papers, 2023). Sudden impairment of blood flow to a part of the brain due to occlusion or rupture of an artery to the brain. "Given the increase in actin sliding velocity, we next sought to determine whether the D515N mutation alters the mechanical or kinetic properties of the MYH7b working stroke." (PMID 36963494, 2023). "Our data clearly demonstrate a two-substep working stroke for both human and python MYH7b, demonstrating that the mechanics of the MYH7b working stroke are similar to β-MyHC." (PMID 36334627, 2023).
type 2 diabetes (2 papers, 2021 to 2022). "The genetic susceptibility to type 2 diabetes was associated with increased levels of MYH7B in pancreatic tissue (Z = 2.4, Q = 0.008)." (PMID 34575035, 2021). "Transcription factors co-regulating the pancreatic expression of EDEM2, MYH7B, MAP1LC3A, and CPNE1 genes that associated with type 2 diabetes have been predicted by the hTFtarget tool." (PMID 34575035, 2021). "The TWAS analysis has shown that the pancreatic expression of EDEM2, MYH7B, MAP1LC3A, and CPNE1 correlated to a carriage of T2D-associated alleles of GSS and GGT7 is associated with the genetic risk of type 2 diabetes." (PMID 34575035, 2021). "Thus, the TWAS analysis allowed revealing the genetic association between the changes in pancreatic expression of genes such as EDEM2, MYH7B, MAP1LC3A, and CPNE1 and the risk of type 2 diabetes." (PMID 34575035, 2021). "In addition, further TWAS analysis has revealed that the increased pancreatic expression of EDEM2, MYH7B, MAP1LC3A and decreased levels of CPNE1 are associated with the genetic risk of type 2 diabetes." (PMID 34575035, 2021).
bladder cancer (1 paper, 2021). "miR892b modulates the FBLN1, MYH7B and MST1R genes and is known to influence proliferation, migration, and invasion of bladder cancer cells." (PMID 34357026, 2021).
hepatitis C (1 paper, 2015). "Again, a sensitivity analysis deleting hepatitis C patients with non-1 viral genotypes confirmed the lack of a relationship between hepatic MYH7B expression and chronic HCV infection (p = 0.1240, data not shown)." (PMID 26606750, 2015).
hepatocellular carcinoma (1 paper, 2021). A malignant tumor that arises from hepatocytes. "miR892a modulates the FBLN1, MYH7B and MST1R genes and is known to promote proliferation and invasion of hepatocellular carcinoma cells via targeting CD226." (PMID 34357026, 2021).
ischemic cardiomyopathy (1 paper, 2022). Ischemic cardiomyopathy is a cardiomyopathy in which a weakness in the muscle of the heart due to inadequate oxygen delivery to the myocardium with coronary artery disease being the most common cause. "Intriguingly, MYH7b RNA levels were shown to correlate with β-MyHC expression, including the known increase in β-MyHC expression in human hearts from patients with ischemic cardiomyopathy." (PMID 35409153, 2022).
myocardial infarction (1 paper, 2020). Gross necrosis of the myocardium, as a result of interruption of the blood supply to the area, as in coronary thrombosis. "miR-499 are the myocardial cell-specific precursors of miR-499-3p, located in the introns of the myosin gene myh7b, which is almost exclusively produced in the heart and released into the blood from damaged myocardial cells during myocardial infarction." (PMID 32908925, 2020).
myopia (1 paper, 2024). "Because the retina is a neural tissue, the expression of numerous genes linked to cardiac muscle (MYBPC3, ACTC1, MYL3, MYH7, MYH7B) or to skeletal muscle (MYL1, SMYD1, TNNI2, MYH1B, ACTA1, TNNT3) presents a conundrum for explaining a mechanism for myopia progression." (PMID 39028695, 2024).
osteosarcoma (1 paper, 2018). A usually aggressive malignant bone-forming mesenchymal neoplasm, predominantly affecting adolescents and young adults. "Similar to ZNRD1, MYH7B was also found upregulated in chemoresistance osteosarcoma samples." (PMID 29850522, 2018).
viral myocarditis (1 paper, 2019). Myocarditis that is caused by an infection with a viral agent. "The viral myocarditis pathway was the only significantly enriched pathway that was distinct to SF; with associated genes falling in the myosin family (Myh2, Myh3, Myh10 and Myh7b)." (PMID 31253821, 2019).
cancer (3 papers, 2018 to 2022). A tumor composed of atypical neoplastic, often pleomorphic cells that invade other tissues. "The microRNA-499 gene is located in the 20th intron of the Myh7b (beta-myosin heavy chain 7B), and, therefore, it is often associated with cancer risk because it might affect Myh7b gene function." (PMID 32545342, 2020). "At present, MYH7B was mainly involved in pathway of cardiomyocytes, such as mitochondrial apoptosis pathway but studies about cancer were rare." (PMID 29850522, 2018).
heart disease (3 papers, 2013 to 2022). "Six candidate genes including LMNA, Zinc Finger Homeobox 3 (ZFHX3), Matrix Metallopeptidase 2 (MMP2), Angiopoietin-Like 5 (ANGPTL5), Myosin Heavy Chain 7B (MYH7B) and Potassium voltage-gated channel subfamily H member 6 (KCNH6) have been previously linked to heart disease." (PMID 24349489, 2013).
MYH7B also shares sentences with these, for which no sentence is quoted: cardiac hypertrophy (2 papers); congenital myopathy (2); neurodegenerative disease (2); breast carcinoma (1); cardiomyopathy (1); chronic hepatitis C (1); familial restrictive cardiomyopathy (1); glioma (1); heart failure (1); Hip dysplasia (1); ischemic heart disease (1); left ventricular non-compact cardiomyopathy (1); liver diseases (1); muscular dystrophies (1); Obesity (1); Parkinson disease (1); rheumatoid arthritis (1); Sepsis (1); valvular heart disease (1); viral infection (1).